EGFR (epidermal growth factor receptor)
Diseases named in the same sentence as EGFR in open-access papers (continued):
Sharing a sentence is not in itself a finding about the gene and the disease.
endometrial cancer (130 papers, 2008 to 2025). Primary or metastatic malignant neoplasm involving the endometrium (mucous membrane that lines the endometrial cavity). "It has been shown that the gene amplification of HER2 (ERBB2) and overexpression of EGFR (ERBB1) are respectively associated with aggressive types (papillary serous and clear cell histologies) and a poor survival rate among patients with endometrial cancer." (PMID 26849234, 2016). "EGFR is expressed in normal endometrial membrane and its overexpression is associated with the stage of endometrial cancer and a poor prognosis." (PMID 24649249, 2013). "Epidermal growth factor receptor expression has been demonstrated in 43–67% of patients with endometrial cancer and has similarly been associated with significantly shortened disease-free and overall survival." (PMID 18334972, 2008). "EGFR expression is increased in endometrial cancer is associated with poor prognosis." (PMID 27092881, 2016). "Elucidation of the EGFR signaling network also has implications beyond reproductive health as it is overexpressed in approximately 50% of endometrial tumors and is significantly associated with decreased survival in patients with Type II endometrial cancer." (PMID 24945252, 2014). "FH knockdown leads to an increase in the phosphorylation level of epidermal growth factor receptor, thereby promoting the proliferation and metastasis of endometrial cancer." (PMID 41380966, 2025). "While in Ureteral DARs, their related genes enriched in kidney disease connected pathway, such as Wnt signaling pathway, Endometrial cancer and EGFR-TKI resistance." (PMID 40034749, 2025). "In endometrial carcinoma, a significant correlation between EGFR expression and grade, metastasis, myometrial invasion, and age has been found." (PMID 40422510, 2025). "In endometrial cancer, EGFR has been shown to be activated, leading to endometrial cancer progression." (PMID 39194522, 2024). "When FH was overexpressed in endometrial cancer cells, the proliferative, migratory and invasive capacity of these cells was reduced, accompanied by partial inactivation of EGFR." (PMID 39403185, 2024). "Among these, lapatinib, a dual inhibitor targeting both HER2 (ErbB2) and EGFR (ErbB1), has been extensively studied for its efficacy in many cancer types, including endometrial carcinoma." (PMID 39768892, 2024). "To date, the reasons for progestin resistance in endometrial cancer include overexpression of epidermal growth factor receptor (EGFR) and activation of the PI3K/Akt pathway." (PMID 38250737, 2023). "In this study, KLE cells (derived from undifferentiated endometrial carcinoma) were used as the positive controls in an analysis of the cellular expression of EGFR and ErbB4." (PMID 37231448, 2023). "A phase II study in recurrent or metastatic endometrial cancer utilizing the selective inhibitor of the EGF receptor (EGFR) tyrosine kinase activity erlotinib showed a low response rate of 12.5%, although it is well tolerated." (PMID 35328833, 2022). "Endometrial carcinoma cells express EGFR, and they represent a good model to investigate the role of EGF in cancer cell proliferation." (PMID 36123565, 2022). "We observed that PI3K/AKT and EGFR serve as key kinases that have roles as growth suppressors of Hec-1A endometrial cancer cells by mediating the LRIG2-induced modulation of the BCL-2 family of proteins and p21." (PMID 29358688, 2018). "Overexpression of EGFR has been detected in endometrial carcinoma, correlating with advanced tumor grade, metastasis, and poor prognosis." (PMID 30510261, 2018). "We found that SOX2 knockdown inhibited EGFR expression and attenuated cell proliferation in endometrial carcinoma cells." (PMID 30510261, 2018).
endometrial cancer (continued). "EGF treatment of endometrial carcinoma cells was reported to induce an EGFR-dependent RIP of EpCAM, resulting in complete EpEX shedding from the membrane and in release of EpICD, which serves as a nuclear transcriptional inducer of an EMT program." (PMID 30261040, 2018). "Despite the success of EGFR inhibitors in other malignancies, discouraging results have been observed in endometrial cancer owing to low response rates to drugs." (PMID 28184290, 2017). "EGFR overexpression is common in endometrial cancer and has been correlated with tumor grade, deep myometrial invasion, and poor prognosis." (PMID 28184290, 2017). "We also demonstrated that NMU signaling not only promotes the progression of endometrial cancers but also positively modulates the sensitivities of EGFR and TGFβ receptor via the control of adhesion signaling." (PMID 26849234, 2016). "This study investigates the mechanism and functional consequences of MUC1 driven EGFR expression and signaling in endometrial cancer." (PMID 27092881, 2016). "This study shows that MUC1 increases EGFR mRNA and protein expression in endometrial cancer cells, extending observations as reported in other cell types." (PMID 27092881, 2016). "We observed indications that MUC1 driven EGFR regulation occurs in endometrial cancers and is likely manifest at two levels: 1) by elevating EGFR levels transcriptionally and; 2) by enhancing EGFR signaling." (PMID 27092881, 2016). "Two EGFR inhibitors have been tested in clinical trials for advanced or recurrent endometrial cancer." (PMID 27092881, 2016). "In this study, we confirmed that the amount of EGFR expression plays an important role in MAPK pathway in endometrial cancer cell, suggesting that endometrial cancer with highly expressed EGFR is strongly effected by anti-EGFR drugs." (PMID 26673416, 2015). "As a first step, IHC was carried out on endometrial carcinoma to confirm the expression of EGFR and HER-2 proteins." (PMID 26673416, 2015). "We found that erlotinib, a known potent selective inhibitor of the EGFR tyrosine kinase, significantly inhibits the proliferation of endometrial carcinoma cells, which express high levels of EGFR in xenograft mice models." (PMID 26673416, 2015). "We examined the molecular factors that underlie the variable responsiveness to erlotinib in accordance with the expression levels of both EGFR mRNA and EGFR protein in the endometrial carcinoma cells, using quantitative RT-PCR and IHC." (PMID 26673416, 2015). "Targeting of molecules in the carcinogenic pathways of endometrial cancer includes the use of human epidermal growth factor receptor (EGFR) inhibitors, such as gefitinib, erlotinib and cetuximab." (PMID 24649249, 2013). "In order to verify that estrogen-induced GPR30 signaling is mediated through EGFR/PI3K/FAK pathway in endometrial cancer cells, we used specific inhibitors or siRNA to test this pathway." (PMID 24039841, 2013). "In conclusion, we demonstrated for the first time that estrogen- and antiestrogen-induced migration of endometrial cancer cells was through GPR30 signaling and activation of EGFR/PI3K/ERK/FAK pathway in endometrial cancer cells." (PMID 24039841, 2013). "Both inhibitors blocked estrogen-mediated nuclear accumulation of the PH-RFP reporter, indicating a requirement for both HB-EGF and EGFR in estrogen-mediated PI3K activation in Hec50 endometrial cancer cells." (PMID 24379833, 2013). "Epidermal growth factor (EGF) and its receptor (EGFR) constitute a principal growth-promoting pathway in endometrial cancer cells." (PMID 20579378, 2010). "Type I Ishikawa H and type II Hec50co endometrial carcinoma cells both express EGFR and sEGFR, but differ markedly in their responsiveness to the EGFR inhibitor gefitinib." (PMID 20579378, 2010). "Recently, we were able to demonstrate significant preclinical activity of a dual HER2 and EGFR kinase inhibitor in endometrial cancer cell lines with HER2 amplification or EGFR expression." (PMID 19088718, 2009).
endometrial cancer (continued). "Our laboratory data provide a clear biologic rational to test lapatinib as a single agent or in combination with chemotherapy in HER2-overexpressing and/or possibly EGFR-expressing endometrial cancer." (PMID 18334972, 2008). "All of the remaining established human endometrial cancer cell lines expressed varying but lower levels of EGFR compared with the HEC155, SNG-II, SNG-M, or RL-95-2 cells." (PMID 18334972, 2008). "The effects of lapatinib on human endometrial cancer cells were evaluated using a panel of 19 established endometrial cancer cell lines that expresses widely varying levels of EGFR and HER2." (PMID 18334972, 2008). "Among the peptide growth factor receptors frequently implicated in endometrial cancer are members of the type I receptor tyrosine kinase family, which includes HER1 (epidermal growth factor receptor (EGFR)), HER2, HER3, and HER4." (PMID 18334972, 2008). "Certain signaling pathways were differentially targeted by miR-146a-5p in various cancers, including LIF-Stat3 when reported in the endometrium of patients with implantation failure, NOTCH 1/2 in endometrial carcinoma, and the EGFR, NF-κB, TGF-β, and SMAD4 pathways in other tumor types." (PMID 37240034, 2023). "Furthermore, BPA can bind to the ERRγ of endometrial cancer cells, which can activate the epidermal growth factor receptor (EGFR)/extracellular signal-regulated kinase (ERK) pathway associated with proliferation." (PMID 36011004, 2022). "Erlotinib and gefitinib, two epidermal growth factor receptor (EGFR) and tyrosine kinase inhibitors, have also been tested in patients with endometrial cancer, as EGFR is overexpressed in 40–46% of Type I endometrial carcinoma cases, and in 34% of Type II endometrial carcinomas." (PMID 34357126, 2021). "A significant amount of EGFR expression is found in endometrial cancer." (PMID 31583159, 2019). "In addition, oncogene, fibroblast growth factor receptor 2 (FGFR2), P13KCA, and epidermal growth factor receptor (EGFR) are also playing a necessary role in endometrial cancer." (PMID 31583159, 2019). "The overexpression of EGFR is found in several cancers including endometrial cancer." (PMID 31583159, 2019). "In addition, we discovered that SOX2 induces EGFR in a positive feedback manner, contributing to cell cycle progression and migration of endometrial cancer cells." (PMID 30510261, 2018). "In endometrial cancer, loss of polarity coupled with elevated expression of both MUC1 and EGFR could enhance the activity of this positive feedback loop." (PMID 27092881, 2016). "After overexpressed of miR-490-3p in endometrial cancer cells the expression of TGFα was decreased, while EGFR and the downstream related genes including NF-kB, MMP-2, Cyclin D1, survivin were decreased in mRNA and protein level, while increased Bax expression." (PMID 26843615, 2016). "It would follow that co-targeting of MUC1 and EGFR in endometrial cancer could provide a more effective therapy than targeting EGFR alone." (PMID 27092881, 2016). "It is possible that MUC1 and EGFR targeted co-therapies may provide a new avenue for the treatment of advanced endometrial cancer." (PMID 27092881, 2016). "We show for the first time that MUC1 stimulates EGFR expression and function in endometrial cancer." (PMID 27092881, 2016). "Future evaluation of advanced endometrial cancer for MUC1 and EGFR expression followed by co-targeting may provide a new avenue for the treatment of advanced endometrial cancer." (PMID 27092881, 2016). "However, the present data demonstrate that erlotinib has efficacy in the treatment of endometrial cancers, which highly express EGFR." (PMID 26673416, 2015).
endometrial cancer (continued). "To evaluate the potential therapeutic effects of tyrosine kinase inhibitors in the treatment of endometrial cancer, we previously have characterized the EGFR pathway in endometrial cancer cells at the signaling level, with respect to cell cycle, and now at the genomic level." (PMID 20579378, 2010). "The small cluster of differently regulated genes reported here in these type I vs. type II endometrial cancer-derived cell lines may identify candidate biomarkers useful for predicting sensitivity to EGFR blockade." (PMID 20579378, 2010). "Immunohistochemical analysis using 63 surgical specimens of endometrioid-type endometrial cancers revealed that EGFR, human epidermal growth factor receptor (HER)-2 and HER-4 were expressed in 25 (39.7%) of 63, 26 (41.3%) of 63 and 31 (49.2%) of 63 tumours, respectively." (PMID 20664599, 2010). "The purpose of these studies was to explore the genomic pathways activated or inhibited downstream of EGFR in cells that are model of type I endometrial cancer and somewhat responsive to tyrosine kinase activation or inhibition versus those type II endometrial cancer that are resistant." (PMID 20579378, 2010). "Some genes related with endometrial carcinoma prognosis have become a hopeful target for therapies in endometrial carcinoma, these targeting genes include mTOR inhibitors, EGFR tyrosine kinase inhibitors (erlotinib), and monoclonal antibodies to Her-2/neu (trastuzumab)." (PMID 20613958, 2010). "Preclinical data suggest that EGFR inhibitors may be clinically active in well-defined subgroups of endometrial cancer patients with HER2 gene amplification or high levels of EGFR expression." (PMID 19088718, 2009). "EGFR expression is increased in various cancer types, including endometrial cancer." (PMID 19917135, 2009). "The current preclinical data suggest that EGFR inhibitors may also be clinically active in well-defined subgroups of endometrial cancer." (PMID 18334972, 2008). "Multiple drug effect analysis was performed using two HER2-overexpressing and two EGFR-expressing established endometrial cancer cell lines to determine the nature of the interaction between lapatinib and carboplatin, paclitaxel, doxorubicin, or docetaxel (synergy, addition, or antagonism)." (PMID 18334972, 2008). "Exposure of USPC1, USPC2, RL-95-2, HEC155, and SNG-II human endometrial cancer cells to lapatinib resulted in a dose-dependent reduction of phosphorylation of both the EGFR and HER2 receptor tyrosine kinases and their downstream signalling intermediates AKT and ERK." (PMID 18334972, 2008). "Similarly, agonistic activity of tamoxifen increases the proliferation of endometrial cancer cells by activating the GPER-1/EGFR/ERK1/2/CyclinD1 route, data that is in agreement with the observation that endometrial cancer patients under tamoxifen treatment exhibit a worse prognosis." (PMID 33117280, 2020). "EGFR polymorphisms do not contribute to poor prognosis in endometrial cancer." (PMID 27092881, 2016). "The role of EGFR gene amplification or mutations in endometrial cancer has not been studied yet." (PMID 18334972, 2008). "Finally, we used multiple drug effect/combination index (CI) isobologram analysis to study the efficacy of chemotherapeutic drugs plus lapatinib combinations tested against lapatinib-sensitive HER2-amplified/overexpressing or EGFR-expressing endometrial cancer cells." (PMID 18334972, 2008). "On the opposite end, two CDNs with imax > 20 are observed in only one cancer type (EGFR: T2573 in lung and FGFR2: C755 in endometrium cancer)." (PMID 39688957, 2024).
endometrial cancer (continued). "Among them, the key players are PIK3CA, BRAF, and epidermal growth factor receptor (EGFR), which activate various tumor cell signaling pathways in endometrial cancer cells." (PMID 35264951, 2022). "The expression of Egr-1 in breast and endometrial cancer cells is stimulated by E2 and hydroxytamoxifen (OHT) and mediated via GPER/EGFR/ERK signaling and in model cell lines (breast and endometrial cancer cells)." (PMID 36558071, 2022). "Overexpressed MUC20 activates the EGFR-STAT3 pathway, promotes epidermal growth factor receptor (EGF) expression, and induces a malignant phenotype of endometrial cancer." (PMID 36553184, 2022). "EGFR inhibitors, Her-2 inhibitors, MEK inhibitor and MET inhibitor in metastatic, advanced or recurrent endometrial cancer." (PMID 34944775, 2021). "Molecular alterations of EGFR and PIK3CA, which are found in the endometrial cancer signaling network, have been reported in endometrial cancer studies." (PMID 29912931, 2018). "In this study, we investigated if Gefitinib, an epidermal growth factor receptor (EGFR) inhibitor, augments endometrial cancer (EC) therapy with medroxyprogesterone acetate (MPA)." (PMID 29383165, 2017). "With CD44 playing as an auxiliary receptor in promoting growth factor receptor activities, this explains how NMU signaling also tightly controls the intensity of EGFR-driven and TGFβ receptor-driven EMT in endometrial cancer cells." (PMID 26849234, 2016). "Therefore, combined therapy that includes targeting of NMU signaling may enhance the efficacy of current drugs that are designed to inhibit EGFR and/or TGFβ receptor pathways; such an approach could be beneficial when treating patients with aggressive endometrial cancer." (PMID 26849234, 2016). "Lapatinib is an inhibitor targeting EGFR and HER2 that is currently being evaluated in the GOG 229-D phase II trial for recurrent endometrial cancer." (PMID 24649249, 2013). "In this study, we found frequent expressions of EGFR, HER-2 and HER-4 approximately in 40–50% of endometrioid-type endometrial cancer." (PMID 20664599, 2010). "Our primary aim was to explore the in vitro effects of this dual receptor tyrosine kinase inhibitor (TKI) in an unbiased way using a large panel of 19 endometrial cancer lines that express variable levels of HER2 and EGFR." (PMID 18334972, 2008). "In this study, we explore the therapeutic potential of lapatinib a selective inhibitor of both the EGFR and HER2 tyrosine kinases for the treatment of endometrial cancer." (PMID 18334972, 2008). "After quantitation of EGFR and HER2 receptor levels in the endometrial cancer cell lines, growth assays were performed." (PMID 18334972, 2008). "Therefore, we further determined the expression levels of CDC6, EGFR, and HAUS6 during PCOS carcinomatosis to endometrial carcinoma." (PMID 39684684, 2024). "However, taking EGFR expression levels/mutations into consideration could improve clinical outcomes, as in vitro and in vivo studies showed an anti-tumor effect of erlotinib only in EGFR high level, although not low level endometrial cancer cells." (PMID 35328833, 2022). "However, in endometrial cancer, MUC20 overexpression drives tumourigenesis, predicts poor survival, and EGF-induced malignant phenotypes were enhanced by activating the EGFR/STAT3 pathway." (PMID 36059804, 2022). "Hence, we further characterized how SOX2 crosstalks with EGFR and TGF-β signaling to affect cancer cell growth and dissemination in endometrial carcinoma." (PMID 30510261, 2018). "We will be focusing on the uses of anti-angiogenic agents, epidermal growth factor receptor (EGFR) inhibitors, HER2/neu antibodies, and phosphoinositide 3-kinase (PI3K)-PTEN-AKT-mammalian target of rapamycin (mTOR) pathway inhibitors in endometrial cancer (seeTable 1)." (PMID 28184290, 2017). "The combined influence of MUC1 and EGFR has not been studied in endometrial cancer and any physiological or clinical relevance of their co-regulation is not known." (PMID 27092881, 2016).